RAB21 (RAB21, member RAS oncogene family)
Description:
The small GTPases Rab are key regulators of intracellular membrane trafficking, from the formation of transport vesicles to their fusion with membranes. Rabs cycle between an inactive GDP-bound form and an active GTP-bound form that is able to recruit to membranes different sets of downstream effectors directly responsible for vesicle formation, movement, tethering and fusion. RAB21 is involved in membrane trafficking control. During the mitosis of adherent cells, controls the endosomal trafficking of integrins which is required for the successful completion of cytokinesis. Regulates integrin internalization and recycling, but does not influence the traffic of endosomally translocated receptors in general (By similarity). As a result, may regulate cell adhesion and migration (By similarity). Involved in neurite growth (By similarity). Following SBF2/MTMT13-mediated activation in response to starvation-induced autophagy, binds to and regulates SNARE protein VAMP8 endolysosomal transport required for SNARE-mediated autophagosome-lysosome fusion. Modulates protein levels of the cargo receptors TMED2 and TMED10, and required for appropriate Golgi localization of TMED10.
Synonyms: KIAA0118
Tractability: Small molecule: a structure with a bound ligand is known; it has a binding pocket of medium quality. PROTAC: ubiquitination databases record sites on it; its protein half-life has been measured.
Gene: Protein-coding gene on chromosome 12 (71,754,863 to 71,800,286, forward strand). Ensembl gene ENSG00000080371.
Subcellular location: Endoplasmic reticulum membrane; Golgi apparatus, trans-Golgi network; Golgi apparatus membrane; Early endosome membrane; Cytoplasmic vesicle membrane; Cleavage furrow; Cell projection, neuron projection
Pathways (Reactome):
Metabolism of proteins: RAB geranylgeranylation
Vesicle-mediated transport: RAB GEFs exchange GTP for GDP on RABs
Gene Ontology:
Molecular function: G protein activity; GDP binding; GTP binding; GTPase activity; protein binding
Biological process: anterograde axonal transport; positive regulation of early endosome to late endosome transport; positive regulation of receptor-mediated endocytosis; protein stabilization; regulation of exocytosis; positive regulation of dendrite morphogenesis; Rab protein signal transduction; regulation of axon extension
Cellular component: cleavage furrow; cytoplasmic side of early endosome membrane; cytoplasmic side of plasma membrane; cytoplasmic vesicle membrane; early endosome membrane; endoplasmic reticulum membrane; endosome; extracellular exosome; focal adhesion; Golgi cisterna membrane; trans-Golgi network; vesicle membrane; cytosol; early endosome; axon cytoplasm; Golgi apparatus; Golgi membrane; neuron projection; synapse
Genetic constraint (gnomAD): Loss-of-function variants: 6 observed, 8.71 expected, observed/expected ratio (o/e) 0.69, 90% interval 0.38 to 1.35. That is too few expected variants to judge how well the gene tolerates losing a copy. Missense variants: 135 observed, 116.84 expected, observed/expected ratio (o/e) 1.16, 90% interval 1 to 1.33. Synonymous variants: 51 observed, 45.78 expected, observed/expected ratio (o/e) 1.11, 90% interval 0.89 to 1.41.
Homologues: Orthologues: chimpanzee RAB21 (99% identical), macaque RAB21 (97% identical), mouse Rab21 (96% identical), pig RAB21 (96% identical), rabbit RAB21 (96% identical), rat Rab21 (96% identical), tropical clawed frog rab21 (90% identical), zebrafish rab21 (84% identical), guinea pig RAB21 (73% identical), Drosophila melanogaster Rab21 (51% identical), Caenorhabditis elegans rab-21 (48% identical). Paralogues in human: RAB5A (39% identical), RAB5C (39% identical), RAB22A (37% identical), RAB17 (36% identical), RAB43 (36% identical), RAB11B (36% identical), RAB5B (36% identical), RAB11A (35% identical), RAB31 (35% identical), RAB14 (35% identical), RAB27A (33% identical), RAB2A (33% identical), and 56 more.